TSR2 (TSR2 ribosome maturation factor)
Description:
May be involved in 20S pre-rRNA processing.
Synonyms: DT1P1A10; RP1-112K5.2; WGG1; DBA14
Tractability: PROTAC: ubiquitination databases record sites on it; its protein half-life has been measured.
Gene: Protein-coding gene on chromosome X (54,440,402 to 54,448,032, forward strand). Ensembl gene ENSG00000158526.
Subcellular location (Human Protein Atlas): Nucleoli; Nucleoplasm; Cytosol
Gene Ontology:
Molecular function: protein binding
Biological process: maturation of SSU-rRNA from tricistronic rRNA transcript (SSU-rRNA, 5.8S rRNA, LSU-rRNA)
Cellular component: nucleus
Homologues: Orthologues: chimpanzee TSR2 (100% identical), rabbit TSR2 (90% identical), dog TSR2 (87% identical), rat Tsr2 (87% identical), mouse Tsr2 (86% identical), pig TSR2 (85% identical), guinea pig TSR2 (84% identical), macaque TSR2 (74% identical), zebrafish tsr2 (42% identical), tropical clawed frog tsr2 (28% identical), Drosophila melanogaster CG14543 (25% identical), Caenorhabditis elegans tsr-2 (22% identical).
Diseases named in the same sentence as TSR2 in open-access papers:
TSR2 is named in the same sentence as 16 diseases in open-access papers, as found by Europe PMC text mining. Sharing a sentence is not in itself a finding about the gene and the disease. The quoted sentences say what the papers report.
Diamond-Blackfan anemia (4 papers, 2015 to 2025). A congenital aregenerative and often macrocytic anemia with erythroblastopenia. "Moreover, mutations in genes encoding RPS26 and TSR2 were associated with hematopoiesis impairment that underlies the genetic blood disorder Diamond-Blackfan anemia (DBA)." (PMID 40377206, 2025). "Notably, ribosomal subunits were either unchanged or decreased, and several genes implicated in Diamond-Blackfan Anemia (TSR2 ribosome maturation factor [TSR2], RPS26, RPS17) clustered in the group showing the largest decreases in translation efficiency." (PMID 33137094, 2020).
Hypertension (1 paper, 2024). The presence of chronic increased pressure in the systemic arterial system. "TSR2 is highly expressed in individuals with hypertension and may play a significant role in the development of hypertension through the PPAR signaling pathway." (PMID 38814181, 2024). "TSR2 could serve as a molecular target for the early diagnosis and precise treatment of hypertension, providing a valuable direction for the mechanism research of this condition." (PMID 38814181, 2024).
laryngeal carcinoma (1 paper, 2021). Carcinoma that arises from the laryngeal epithelium. "TSR2 can induce apoptosis of laryngeal cancer cells by inhibiting NF-κB signaling pathway." (PMID 34630514, 2021).
microcephaly (1 paper, 2023). A congenital or acquired developmental disorder in which the circumference of the head is smaller than normal for the person's age and sex. "According to GO analysis, these genes are associated with either abnormal hematopoiesis (Aurkb, Fen1, Hrob, Kif20a, Rad51ap1 and Tsr2) or microcephaly (Casc5, Hmgb3, Ncaph and Wdr62), or both (Fanca and Trip13)." (PMID 37661832, 2023).
prostate carcinoma (1 paper, 2021). A carcinoma that arises from epithelial cells of the prostate gland. "In contrast, top hits such as TSR2 are essential for the proliferation or survival of nearly all cell types and thus are almost certainly not prostate cancer-specific driver genes." (PMID 34326322, 2021). "This analysis strategy revealed the Androgen Receptor (AR) as the top prostate cancer-specific gene hit, but the next four top-ranked hits were genes not previously associated with prostate cancer: KIF4A, MRPL13, NDUFB11, and TSR2 (top 5)." (PMID 34326322, 2021).
squamous cell carcinoma (1 paper, 2012). A carcinoma arising from squamous epithelial cells. "When a squamous cell carcinoma cell line transfected with TSR2+RFK was injected into nude mice, TSR2+RFK inhibited in vivo tumor angiogenesis and growth in the mice." (PMID 22509329, 2012).
tumor (2 papers, 2012 to 2014). "One of them, ABT-898, derived from TSR2, is especially potent in multiple models of angiogenesis and tumor growth and reproduces a full spectrum of TSP1 angioinhibitory effects." (PMID 25526033, 2014).
TSR2 also shares sentences with these, for which no sentence is quoted: cancer (2 papers); Treacher-Collins syndrome (2); anemia (1); dyskeratosis congenita (1); Fanconi anemia (1); mandibulofacial dysostosis (1); pontocerebellar hypoplasia (1); Primary microcephaly (1); Shwachman-Diamond syndrome (1).